S100A2 (S100 calcium binding protein A2)
Diseases named in the same sentence as S100A2 in open-access papers (continued):
Sharing a sentence is not in itself a finding about the gene and the disease.
nasopharyngeal carcinoma (2 papers, 2015 to 2025). A carcinoma arising from the nasopharyngeal epithelium. "Previous studies have reported that in colorectal and nasopharyngeal cancers, S100A2 promotes tumor progression by enhancing glycolysis through the PI3K-AKT pathway, which upregulates GLUT1 expression." (PMID 40011447, 2025).
pancreatic ductal adenocarcinoma (2 papers, 2020 to 2026). An infiltrating adenocarcinoma that arises from the epithelial cells of the pancreas. "In 3 independent pancreatic ductal adenocarcinoma cohorts (total participants = 1184) the relationship between aberrant expression of prometastatic proteins S100A2 and S100A4 and survival was assessed." (PMID 32675551, 2020).
papillary thyroid carcinoma (2 papers, 2022 to 2025). "Previous clinical studies also reported significant differences in S100A2 RNA and protein levels in lymph node metastases of papillary thyroid carcinoma, consistent with our study." (PMID 41374320, 2025). "Research by Ito found that in two types of cancer originating from thyroid follicular cells, most cases of papillary carcinoma were S100A2 positive, while all cases of follicular carcinoma were negative." (PMID 41374320, 2025). "S100A2 plays a specific role in the progression of papillary thyroid carcinoma." (PMID 41374320, 2025). "Moreover, the higher the degree of tumor dedifferentiation (higher invasiveness), the higher the expression of S100A2, such as in anaplastic carcinoma, where S100A2 expression is higher than in papillary carcinoma." (PMID 41374320, 2025). "Although 89.5% of thyroid papillary carcinomas show positive expression of S100A2 in vivo, the detailed prognostic impact of S100A2 in thyroid papillary carcinoma remains unclear." (PMID 35885660, 2022).
renal cell carcinoma (2 papers, 2022 to 2025). "Overexpression of S100A2 significantly enhances the migratory and invasive capabilities of renal cell carcinoma cells, while its knockout inhibits these abilities." (PMID 40011447, 2025). "Although the prognostic influence remains unclear, lower S100A2 expression in renal cell carcinoma might be expected to be advantageous for tumor development." (PMID 35885660, 2022). "Immunofluorescence experiments showed that S100A2 and HNF1A were significantly co-localized in the nucleus in clear renal cell carcinoma cells and in HEK293T cells, supporting the interaction between S100A2 and HNF1A." (PMID 40011447, 2025).
renal tumors (2 papers, 2009 to 2017). "Specifically, the transcript expressions of AKR1C1, S100A2, PLAU, SLC3A2, TBC1D2, and WIZ were decreased, while expressions of TGM2, SLC7A5, and NMI were increased in renal tumors when compared with non-tumorous control samples." (PMID 29272308, 2017).
small cell lung carcinoma (2 papers, 2021 to 2025). Small cell lung cancer (SCLC) is a highly aggressive malignant neoplasm, accounting for 10-15% of lung cancer cases, characterized byrapid growth, and early metastasis. "Diminished S100A2 expression was shown to correlate with increased methylation in small cell lung cancer cells and metastatic head and neck cancer (Leśniak, 2011)." (PMID 34485305, 2021).
Stevens-Johnson syndrome (2 papers, 2021). Stevens-Johnson syndrome is a limited form of toxic epidermal necrolysis characterized by destruction and detachment of the skin epithelium and mucous membranes involving less than 10% of the body surface area. "We performed immunostaining for S100A2 in the skin and evaluated the difference in its distribution in the epidermis between mild and severe forms of drug eruptions such as Stevens-Johnson syndrome and toxic epidermal necrolysis." (PMID 33750880, 2021).
thyroid cancer (2 papers, 2020 to 2022). "It has been previously reported that the S100 proteins S100A2, S100A4, S100A6, and S100A9 are upregulated in thyroid cancer and that these subfamily members are involved in the progression of cancer in different ways." (PMID 32015423, 2020).
toxic epidermal necrolysis (2 papers, 2021). Toxic epidermal necrolysis (TEN) is an acute and severe skin disease with clinical and histological features characterized by the destruction and detachment of the skin epithelium and mucous membranes. "Severe-type drug eruption in patients with toxic epidermal necrolysis due to phenytoin and celecoxib was related to high expression of S100A2 in the spinous layer of the epidermis." (PMID 33750880, 2021).
uveal melanoma (2 papers, 2009 to 2010). A melanoma derived from melanocytes of the uveal tract. "In an in vitro model of uveal melanoma, S100A2 gene expression was significantly up-regulated by the methyltransferase inhibitor decitabine, which was correlated with cell death." (PMID 19859558, 2010).
aristolochic acid nephropathy (1 paper, 2024). "S100A2 levels were evaluated in three mouse models, including unilateral ureteral obstruction (UUO), ischemia-reperfusion injury (IRI), and aristolochic acid nephropathy (AAN), as well as in TGF-β1- treated HK-2 cells and in kidney tissue samples." (PMID 39382800, 2024).
basal cell carcinoma (1 paper, 2015). A carcinoma involving the basal cells. "Furthermore, in a previous report, S100A2 overexpression in squamous and basal cell carcinoma was often found to be associated with hyperplastic peri-lesional skin, and S100A2 presence in this cases may reflect regenerative squamous differentiation." (PMID 26097874, 2015).
chorioamnionitis (1 paper, 2021). A morphologic finding indicating inflammation of the fetal sac membranes. "In addition, while the members of the S100A family are broadly engaged in various regulatory processes of inflammatory diseases, such as Kawasaki disease, ischemic heart inflammation, chorioamnionitis, and eye inflammation, no research has been conducted on the S100A2 gene in ASD immunity so far." (PMID 34746237, 2021).
colon adenocarcinoma (1 paper, 2023). "Interesting, after calculating the comprehensive signature of KRT6A and S100A2 in CRC tissues (including colon adenocarcinoma and rectum adenocarcinoma), we found that the signature score derived from KRT6A and S100A2 was higher in CRC tissues compared non-tumor tissues." (PMID 37647260, 2023).
ependymoma (1 paper, 2008). A WHO grade II, slow growing tumor of children and young adults, usually located intraventricularly. "Candidates (CHI3L1, S100A10, S100A4, S100A6 and S100A2) were validated using immunohistochemistry on a tissue microarray of 74 paediatric ependymoma." (PMID 18781180, 2008). "Protein expression levels of S100A10, S100A6, S100A4 and S100A2 were determined by immunohistochemistry using an independent cohort of seventy-four primary paediatric ependymoma arrayed on a tissue microarray." (PMID 18781180, 2008). "Analysis of all 1q S100 genes represented in SAGE Genie identified S100A2 as the only S100 gene expressed in ependymoma but not expressed at any level in ‘normal’ brain." (PMID 18781180, 2008). "S100A2 was the only S100 gene that was expressed in ependymoma but not in normal brain with mean tag counts of 1.5 and zero, respectively." (PMID 18781180, 2008).
gastric adenocarcinoma (1 paper, 2015). "Another study on samples of gastric adenocarcinoma pointed out that loss of S100A2 expression was significantly associated with lymph node metastasis, lymphatic vessel invasion, and depth of invasion." (PMID 25874882, 2015).
glioblastoma (1 paper, 2022). The most malignant astrocytic tumor (WHO grade IV). "Furthermore, S100A2 is also epigenetically regulated by DNA methylation of CpG islands, and high S100A2 expression is related to glioblastoma tumor cell proliferation, apoptosis, invasion, and migration in vivo." (PMID 35885660, 2022).
Hodgkins lymphoma (1 paper, 2024). A heterogeneous group of malignant lymphoid neoplasms of B-cell origin characterized histologically by the presence of Hodgkin and Reed-Sternberg (HRS) cells in the vast majority of cases. "High-grade non-Hodgkin’s lymphoma demonstrated a moderate S100A2 signal, whereas lymph node, low-grade non-Hodgkin’s lymphoma, and Hodgkin’s lymphoma yielded negative S100A2 signals." (PMID 38684596, 2024).
Hypertension (1 paper, 2020). The presence of chronic increased pressure in the systemic arterial system. "Some of the modulated proteins in saliva such as HSPA8 or S100A9 have been previously related to DM complications such as hypertension or micro-vascular alterations, while others such as S100A2 and S100A11 are described in DM here for the first time." (PMID 33271797, 2020).
laryngeal carcinoma (1 paper, 2015). Carcinoma that arises from the laryngeal epithelium. "In the immunohistochemical analysis of 62 untreated laryngeal carcinoma patients, Libero Lauriola noted a higher level of S100A2 was associated with well-differentiated tumors and less lymph node involvement." (PMID 25874882, 2015). "Functional studies indicated that S100A2 tends to affect the ability of laryngeal cancer cells to migrate and invade." (PMID 25874882, 2015). "Since uncontrolled cell growth and invasion/metastasis are two characteristic features of cancer, we investigated whether S100A2 could play a tumor suppressor role in certain laryngeal cancer cell lines by inhibiting cell invasion and migration." (PMID 25874882, 2015). "The dramatic increase of S100A2 in laryngeal carcinoma tissues suggests that S100A2 is involved in metabolic processes that are not only involved in the biosynthesis of laryngeal carcinoma cells, but also are crucial for the carcinoma cells abilities to migrate and invade." (PMID 25874882, 2015). "Moreover, the S100A2 staining intensity in IHC was stronger in the laryngeal cancer samples." (PMID 25874882, 2015). "As the overexpression of S100A2 was detected in laryngeal cancer and siRNA gene knockdown abrogates cell invasion and migration, S100A2 could be also developed into a biomarker of malignancy in laryngeal cancer." (PMID 25874882, 2015). "It noted up-regulation of S100A2, FGB, KRT17, FN1 and POSTN in laryngeal carcinoma tissues, as compared with normal tissue." (PMID 25874882, 2015). "Specifically, 55/60 (92%) of laryngeal carcinoma samples expressed S100A2, as opposed to 15/20 (75%) in non-tumor samples." (PMID 25874882, 2015). "A significant number of laryngeal carcinoma tissues had higher levels of S100A2 than in matched or unmatched non-tumor adjacent tissues." (PMID 25874882, 2015).
mastitis (1 paper, 2024). Inflammation of breast tissue during lactation or postpartum due to an obstructed duct or infection. "S100 calcium-binding protein A2 was identified in milk from cows with clinical mastitis, but later it was identified also in milk from healthy cows." (PMID 38540408, 2024).
metastatic tumors (1 paper, 2025). "Seven weeks later, the S100A2-OE group exhibited a higher number of metastatic tumors in lung tissues." (PMID 40011447, 2025).
periodontitis (1 paper, 2019). An acute or chronic inflammatory process that affects the tissues that surround and support the teeth. "On the other hand, FABP5 can regulate the production of prostaglandin E2 and S100A2 is associated with inflammatory processes such as periodontitis and constitutes a candidate for biomarker of inflammation in this context." (PMID 30648003, 2019).
renal carcinoma (1 paper, 2025). A carcinoma arising from the epithelium of the renal parenchyma or the renal pelvis. "We further confirmed the association between high S100A2 expression and patient prognosis using the renal cancer dataset (E-DKFZ-1) from the ArrayExpress database." (PMID 40011447, 2025).
renal fibrosis (1 paper, 2024). A final common manifestation of a wide variety of chronic kidney diseases characterized by glomerulosclerosis and tubulointerstitial fibrosis. "We investigated whether S100A2 is associated with renal fibrosis by conducting experiments on HK-2 renal tubular epithelial cell line, which is most sensitive to injury stimuli." (PMID 39382800, 2024). "To delve into the specific role of S100A2 in renal fibrosis, we conducted in vitro experiments involving both gene knockdown and overexpression of S100A2." (PMID 39382800, 2024). "A schematic diagram of the underlying mechanisms by which S100A2 regulates EMT and renal fibrosis." (PMID 39382800, 2024). "S100 calcium-binding protein A2 has long been recognized for its role in tumors, but its relationship with renal fibrosis and its mechanism of action remain unknown." (PMID 39382800, 2024).
schizophrenia (1 paper, 2007). A major psychotic disorder characterized by abnormalities in the perception or expression of reality.
Sepsis (1 paper, 2024). Sepsis is defined as life-threatening organ dysfunction caused by a dysregulated host response to infection. "This study predominantly utilized the highly reliable WGCNA algorithm to conduct co-expression cluster analysis on sepsis and AF datasets, ultimately identifying S100A2 as the core gene shared by sepsis and AF." (PMID 39444551, 2024).
squamous cell lung carcinoma (1 paper, 2017). A carcinoma arising from squamous bronchial epithelial cells. "Desmocollin-3 was the most specific marker for poorly differentiated squamous cell lung carcinoma (100%), followed by CK5/6 (98.3%), glypican-3 (94.8%), Sox2 (94.8%), S100A2 (81%), S100A7 (75.9%), thrombomodulin (72.4%), p63 (48.3%), and HMCK (36.8%)." (PMID 28510121, 2017). "When analyzing only poorly differentiated tumors, HMCK was the most sensitive marker for squamous cell lung carcinoma (100%), followed by p63 (97.8%), CK5/6 (87.0%), Sox2 (71.7%), thrombomodulin (58.7%), desmocollin-3 (52.2%), S100A2 (50%), glypican-3 (45.7%), and S100A7 (45.7%)." (PMID 28510121, 2017).
syringocystadenoma papilliferum (1 paper, 2022). A benign adnexal neoplasm occurring during childhood or adolescence. "Syringocystadenoma papilliferum express S100A2, and calcifying epitheliomas in basophilic cells exhibit positive staining for S100A2." (PMID 35885660, 2022).
tumor (102 papers, 2000 to 2026). "Concurrently, the S100A2+ tumor subset, associated with LNM, fosters an immunosuppressive microenvironment." (PMID 40092486, 2025). "Further research is needed to identify the tumor suppressor role of S100A2 expression associated with adjuvant chemotherapy in well-designed studies using large sample size." (PMID 38316853, 2024). "S100A2 is frequently overexpressed in different types of tumors and is often linked to tumor development." (PMID 38260844, 2023). "This study found that these tumor markers had incredible potential to detect pancreatic carcinoma and strongly showed an inverse association between survival and the presence of three tumor markers (excluding the S100A2 marker)." (PMID 37671217, 2023). "S100A2 is linked to both suppressions of tumor progression as well as being a promoter of carcinogenesis." (PMID 34239729, 2021). "Cox multivariable regression analysis internally and externally validated cytoplasmic S100A2 association with tumor recurrence." (PMID 25591983, 2015). "The identification of genetic damage affecting the S100A2 gene would add weight to the argument that this sequence is causally involved in neoplasia." (PMID 15467767, 2004). "Low cytoplasmic S100A2 may have prognostic value in a patient's survival and is significantly associated with tumour-relating signaling and infiltrating immune cells." (PMID 37476187, 2023). "Moreover, ΔNp63α can interact with BRCA1, the breast/ovarian cancer susceptibility gene, upregulating S100A2 expression and enhancing tumor growth." (PMID 37346040, 2023). "Mechanically, GSEA, ESTIMATE and CIBERSORT algorithm analysis revealed that the deteriorating effect of S100A2 was associated with dysfunctional tumor immune microenvironment, mainly related to lower proportion of CD8+T cells and activated NK cells and higher proportion of M0 macrophages." (PMID 34887861, 2021). "Furthermore, S100A2 was identified as the gene occupying the core position in risk model, which was demonstrated to be significantly associated with the progression of tumor grade, AJCC_stage, age and T stage." (PMID 34887861, 2021). "Methylation differences within the S100A2 gene locus have previously been reported and it is possible that an aberrant lack of methylation of one parental allele could lead to inappropriate expression of the S100A2 gene in tumour tissue." (PMID 15467767, 2004). "Significant genes from transcriptomic data, associated with tumour with low cytoplasmic S100A2, could exhibit the prognostic role in CRC and the relationship between S100A2 and immune infiltration in CRC could inform future CRC treatment which warrants further study." (PMID 37476187, 2023). "Our results suggest that N4BP1 controls multiple targets, such as CCL2, GM-CSF, CXCL8, and S100A2, to regulate multiple tumor malignant behaviors." (PMID 41513619, 2026). "RNA sequencing results revealed significant differences in gene expression, with key genes (upregulated CXCR4, OPCML, and S100A2, and downregulated ATP1A3, CHL1, HLA-DRA, and IL-1β) associated with tumor invasiveness." (PMID 41374320, 2025). "MUC16‐expressing tumor cells are different from S100A2‐expressing tumor cells, and if MUC16 were not part of our panel, about a third of basal‐expressing tumors would be missing." (PMID 39935174, 2025). "Knockdown of S100A2 activates the cGAS/STING pathway, suppressing tumor cell viability and invasiveness, suggesting that S100A2 typically inhibits this pathway." (PMID 39949780, 2025). "The concordance at the protein level was verified by performing dual IHC (GATA6/S100A2) in one case with differential expression and two cases with equivalent RNA expression between the primary tumor and the liver metastasis." (PMID 39935174, 2025). "S100A2 acts as an oncogene in endometrial cancer, promoting tumor aggressiveness through enhanced cell migration, invasion, and EMT." (PMID 39949780, 2025).